CDK12 (cyclin dependent kinase 12)
Diseases named in the same sentence as CDK12 in open-access papers (continued):
Sharing a sentence is not in itself a finding about the gene and the disease.
ovarian carcinoma (continued). "We here report the retrospective analysis of 7 polymorphisms in 5 genes involved in the cellular response to cisplatin (DDP): ATM, ATR, Chk1, Chk2 and CDK12 in a cohort of 240 cancer patients with stage III/IV ovarian cancer underwent surgery and adjuvant chemotherapy." (PMID 27905519, 2016). "The more recently discovered CDK12 appears to act at the 3′-end of the transcription unit and has been identified as a tumor suppressor for ovarian cancer; however much is still unknown about the in vivo roles of CDK12/CyclinK." (PMID 25429106, 2015). "Thus, CDK12/13 likely play an oncogenic role in a large fraction of ovarian cancer patients." (PMID 37202753, 2023). "While the prevalence of CDK12 mutations across ethnic groups has not been fully characterized, there have been some studies highlighting a predisposition for CDK12‐mutated breast and ovarian cancers in patients of Eurasian descent." (PMID 34898046, 2022). "In addition, CDK12(−/−) embryos have reduced expression of genes involved in the DDR and mutations that impair CDK12 kinase activity are associated with misregulation of expression of DNA repair genes and ovarian carcinoma." (PMID 32805052, 2020). "In addition hCDK12 has been identified as a tumor suppressor for ovarian cancer; however much is still unknown about the in vivo roles of CDK12/CyclinK." (PMID 25429106, 2015). "For instance, ovarian cancers that simultaneously express high levels of MYC, CDK12 and CDK13 define a cohort of patients with a pronounced reduction of the overall survival." (PMID 39533070, 2025). "That said, our data are consistent with prior reports describing the inhibitory potential of dual CDK12/13 inhibitor ZSQ836 in HEY and SKOV3 ovarian cancer cell lines and THZ531 in patient-derived ovarian cancer organoids." (PMID 40504161, 2025). "Analysis of the same cohort of patients form the PanCancer project showed that CDK12 and CDK13 deep deletions are mutually exclusive with MYC amplification in ovarian cancer." (PMID 37202753, 2023). "The CDK12 inhibitor reduced the expression of FGFR1 and other FGF receptors in ovarian cancer cells, leading to decreased cell proliferation and increased apoptosis." (PMID 37190191, 2023). "Analysis of data from The Cancer Genome Atlas (TCGA) indicated that the frequency of alterations in the CDK12 (9%) and CDK13 (2.5%) genes was similar (CDK13) or higher (CDK12) with respect to other DDR genes among ovarian cancer patients (n = 398)." (PMID 37202753, 2023). "Other HRR pathway-related genes (ATM, ATR, CDK12, FANCA, FANCD2 and RAD50) were also found to play an essential role in ovarian cancer pathogenesis." (PMID 36729997, 2022). "With the aim of understanding the role of CDK12 in tumor growth and response to therapy better, we used CRISPR/Cas9 technology to generate a CDK12 knock-out system in A2780 ovarian cancer cell lines." (PMID 35912188, 2022). "Among the PPI networks of SYNE1, CDK12, and PGS1, the ovarian and other cancer-related gene SYNE1 is located 19 kb downstream of ESR1, and it partially contributes to ovarian cancer." (PMID 34763659, 2021). "In patient-derived xenografts models from patients with heavily pre-treated ovarian cancer, THZ1 (a chemical that inhibits CDK7, CDK12, and CDK13) repressed MYC expression and suppressed tumor growth." (PMID 33686962, 2021). "Other studies showed that the simultaneous inhibition of CDK12 and CDK13 suppresses tumorigenic features in leukemia, ovarian cancer and triple-negative breast cancer." (PMID 34496885, 2021). "Numerous clinical studies have suggested that CDK12 functions as a tumor suppressor gene in ovarian cancer; however, this status had not been formally confirmed." (PMID 40504161, 2025). "Whether CDK12 functions as a tumor suppressor gene in HGSC, the most common type of ovarian cancer, remains unclear." (PMID 40504161, 2025). "Nevertheless, more than 80% of ovarian cancer patients do not present alterations in the CDK12 and CDK13 genes." (PMID 37202753, 2023).
ovarian carcinoma (continued). "These analyses support the important role played by CDK12 and CDK13 in ovarian cancer." (PMID 37202753, 2023). "However, a recent genomic screen employing six ovarian cancer cell lines indicated that knockout of CDK12 did not alter the response to Olaparib." (PMID 37202753, 2023). "Moreover, recent reports have shown that suppression of MYC via inhibition of CDK7, CDK12 and CDK13 may be an effective treatment for MYC-dependent ovarian cancer." (PMID 32570740, 2020).
gastric cancer (22 papers, 2014 to 2026). A primary or metastatic malignant neoplasm involving the stomach. "In particular, dysregulation of Cdk12 activity has been associated with several types of human cancers, including breast, ovarian, prostate, and gastric cancer, and has highlighted the importance of Cdk12 as a promising diagnostic biomarker and potential therapeutic target." (PMID 38016516, 2023). "While functional studies remain limited, CDK12 knockdown decreases proliferation and migration in gastric cancer cell lines, supporting its classification as a potential prognostic marker and therapeutic target in molecularly defined gastric cancer." (PMID 41491919, 2026). "CDK12, a gene that drives the growth of gastric cancer in humans, triggers the MAPK signaling pathway by directly binding to and phosphorylating PAK2 at T134/T169, which promotes tumor development and cell division." (PMID 39769207, 2024). "In gastric cancer cells, CDK12 phosphorylates PAK2 for activation of the MAPK signaling, and its specific inhibitor Proterol has been approved for clinical trials by the FDA due to positive outcomes obtained from PDX and cell line studies." (PMID 36769170, 2023). "The CDK12 gene has been reported to be one of the driver genes that regulates the growth of gastric cancer." (PMID 36769170, 2023). "The authors found a subgroup of cells between the metastatic group and primary group and discovered some gastric cancer lymph node metastasis marker genes (ERBB2, CLDN11, and CDK12), as well as potential gastric cancer evolution-driving genes (FOS and JUN)." (PMID 37612741, 2023). "The potential of CDK12/PAK2 as a therapeutic target for patients with gastric cancer was highlighted in a previous study." (PMID 37260411, 2023). "Both ERBB2 and CDK12 are located at chromosome 17q12, which is a highly amplified region in gastric cancer." (PMID 37325934, 2023). "Previous studies have shown that the expression level of CDK12 in gastric cancer was correlated with advanced stages and poor outcomes and was positively correlated with the CD8 cell density." (PMID 37260411, 2023). "We found that CDK12 is upregulated in human gastric cancer, and that high expression level of CDK12 is related with a poor overall survival." (PMID 32483448, 2020). "The aim of this study is to identify and characterize the therapeutic potential and related mechanisms of CDK12 in human gastric cancer progression and find an effective CDK12 inhibitor for the treatment of gastric cancer." (PMID 32483448, 2020). "To assess the effect of CDK12 in the growth of human gastric cancer, we utilized a cell xenograft animal model in NU/NU mice with CDK12 stable knock-down SNU-1 cells (2 × 106) with shMock, shCDK12#2 and shCDK12#5." (PMID 32483448, 2020). "The cell viability assay and soft agar colony formation assay showed that knock-down of CDK12 dramatically inhibited gastric cancer viability and anchorage-independent growth." (PMID 32483448, 2020). "Our results showed that the T134/T169 phosphorylated by CDK12 is important for the function of PAK2 in human gastric cancer." (PMID 32483448, 2020). "Our results elucidated a mechanistic basis by which CDK12 drives tumor progression in gastric cancer." (PMID 32483448, 2020). "Down-regulation of CDK12 dramatically decrease gastric cancer cell proliferation and colony formation." (PMID 32483448, 2020). "We further identified FDA approved clinical drug procaterol can serve as an effective CDK12 inhibitor, leading to dramatic restriction of cancer cell proliferation and tumor growth in human gastric cancer cells and PDXs." (PMID 32483448, 2020). "In present study, we aimed to detect the expression of CDK12 protein in gastric cancer and to explore its correlation with patients' clinicopathological features." (PMID 31523177, 2019).
gastric cancer (continued). "In present study, we found that CDK12 was overexpressed in gastric cancer tissues, and its expression was positively correlated with Lauren's classification and high number of metastatic lymph nodes." (PMID 31523177, 2019). "To summary, high expression of CDK12 protein was detected in gastric cancer and was correlated with malignant phenotypes and worse outcome." (PMID 31523177, 2019). "High expression rate of CDK12 was 50%, which was much higher than previously reported CDK12 amplification rate in gastric cancer." (PMID 31523177, 2019). "Positive correlations of CD8+ cell number and CCL21 mRNA expression with CDK12 were identified, which indicated the potential mechanisms of CDK12 regulating biological behavior of gastric cancer." (PMID 31523177, 2019). "Correlation of CDK12 expression with clinicopathological characteristics of gastric cancer patients were analyzed by Pearson's χ2 test." (PMID 31523177, 2019). "Furthermore, CDK12 protein is elevated in gastric cancer and correlates with invasive histology and reduced patient survival." (PMID 39368479, 2024). "An analysis of gastric cancer lymph node metastasis revealed the presence of ERBB2, CLDN11 and CDK12, as markers of lymph node metastasis, which may contribute to lymph node metastasis in gastric cancer." (PMID 37305583, 2023). "Thus, elucidating the functional role and molecular activities of CDK12 in gastric cancer is worthy of investigation." (PMID 32483448, 2020). "In this study, we identified CDK12 as an important therapeutic target for human gastric cancer." (PMID 32483448, 2020). "Among these, CDK12 amplification is mainly detected in HER2-positive gastric cancer." (PMID 32570740, 2020). "We also evaluated CDK12 expression in human gastric cancer cell lines." (PMID 32483448, 2020). "These evidences indicate the involvement of CDK12 in gastric cancer." (PMID 32570740, 2020). "Therefore, correlation of CDK12 expression with CD8+ cell density in gastric cancer was investigated, as well as CC-chemokine ligand 21 (CCL21) expression, a chemokine which can induce T cell infiltration." (PMID 31523177, 2019). "RNA processing or transcriptional effect of CDK12 other than genomic instability maintenance might be the dominant mechanisms to induce T cell infiltration in CDK12 high expression gastric cancer." (PMID 31523177, 2019). "From the results of present study, CCL21 could be one of the potential downstream effect genes of CDK12 in gastric cancer." (PMID 31523177, 2019). "Therefore, the potential downstream effect genes regulated by CDK12 should be investigated in gastric cancer." (PMID 31523177, 2019). "In our pervious study, we first reported amplification of CDK12 in HER2 positive gastric cancer." (PMID 31523177, 2019). "Thus, co‐amplification of CDK12 and ERBB2 may be a potential mechanism underlying trastuzumab resistance in gastric cancer." (PMID 37325934, 2023). "Given the proximity of CDK12 to ERBB2 on chromosome 17q12, co-amplification events likely contribute to its overexpression in HER2-positive gastric cancers." (PMID 41491919, 2026). "CDK12 amplification frequently occurs in HER2-positive breast and gastric cancers, where it enhances PI3K-AKT and WNT signaling." (PMID 41491919, 2026). "Gastric cancer progression is highly correlated with the MAPK signalling pathway, and CDK12 can affect this pathway by phosphorylating the PAK2 gene, leading to the metastasis of gastric cancer." (PMID 38503865, 2024). "SR-4835 is an inhibitor of CDK12/13, and can target HMGA2, thereby indicating a novel mechanism of transition of gastric cancer cells." (PMID 36769170, 2023).
gastric cancer (continued). "Then, we examined the co-localization of CDK12 and PAK2 by laser scanning confocal microscope which revealed that they co-localized in the nuclear and cytoplasm in gastric cancer cells." (PMID 32483448, 2020). "Among five gastric cancer cell lines, SNU-1, KATOIII and NCI-N87 showed a relatively high expression of CDK12." (PMID 32483448, 2020). "Immunohistochemistry staining of CDK12 was performed in all gastric cancer tissues and paired non-tumor tissues." (PMID 31523177, 2019). "Currently, the biological functions of CDK12 in gastric cancer have not been fully investigated." (PMID 31523177, 2019). "Whether CDK12 protein expression is correlated with infiltration of immune cells in gastric cancer has not been investigated." (PMID 31523177, 2019). "Therefore, further investigations should be performed to validate the hypothesis of CDK12/CCL21 pathway in regulation malignant function of tumor cells and immune microenvironment in gastric cancer, as well as the mechanisms of CDK12 regulating CCL21 expression." (PMID 31523177, 2019). "However, expression pattern of CDK12 protein in gastric cancer has not been investigated." (PMID 31523177, 2019).
melanoma (14 papers, 2019 to 2026). A malignant, usually aggressive tumor composed of atypical, neoplastic melanocytes. "In BRAF-mutated melanoma, CDK12 is constitutively activated through phosphorylation by ERK1/2, a key effector of the RAS/MAPK signaling cascade." (PMID 41491919, 2026). "High CDK12 expression was associated with poor prognosis in eight types of cancer, including low-grade glioma, mesothelioma, melanoma and pancreatic cancer." (PMID 38503865, 2024). "Together, these results indicate that SR-4835 efficiently inhibits CDK12/13 activity in BRAF-mutated melanoma, which results in increased DNA damage and reduced cell proliferation." (PMID 38104154, 2023). "To assess the role of CDK12 in melanoma cells, we treated five BRAF-mutated melanoma cell lines (Colo829, A375, WM164, WM983A, WM983B) with increasing concentrations of SR-4835, a recently described ATP-competitive inhibitor of CDK12 and CDK13." (PMID 38104154, 2023). "Consistent with this, we found that several BRAF-mutated melanoma cell lines are more sensitive to CDK12 inhibition (THZ531) (IC50 values between 55 nM and 220 nM) than melanocytes (IC50 > 1 μM)." (PMID 36309522, 2022). "Consistent with this, we found that CDK12 is constitutively activated in BRAF-mutated melanoma and that its inhibition impairs the expression of long genes with multiple exons, including genes involved in the DNA damage response." (PMID 36309522, 2022). "Together, these results suggest that CDK12 is hyperactivated in BRAF-mutated melanoma and that its inhibition reveals prominent synthetic lethal targets." (PMID 36309522, 2022). "To determine the role of CDK12 in melanoma, we performed RNA-sequencing (RNA-seq) on two BRAF-mutated melanoma cell lines (A375 and Colo829) treated with CDK12 inhibitors (THZ531; 500 nM) for 6 h." (PMID 36309522, 2022). "Furthermore, CDK12 mutations in melanoma are already known to impact immunotherapy response Analysis of Reduced CDK12/13 expression in metastatic melanoma patients significantly predicted improved survival and response to immune checkpoint blockade." (PMID 41491919, 2026). "BRAF-mutated melanoma cells were recently shown to display high CDK12 activity." (PMID 38104154, 2023). "Patients with melanoma, bladder and kidney cancers that exhibit mismatch repair deficiency (dMMR), cyclin dependent kinase 12 (CDK12) loss and high tumour mutational burden characterised by good T cell infiltration tend to respond well to ICIs as compared to patients with PCa." (PMID 33921181, 2021). "Similar to CDK12 loss, CDK13 mutations lead to the accumulation of short RNAs and prematurely terminated intronic RNAs, which can accelerate melanoma oncogenesis." (PMID 41491919, 2026). "Treatment of melanoma B16–F10 cells with CDK12/13 PROTAC YJ1206 results in STING signaling activation." (PMID 41491919, 2026). "Similar phenomena of ferroptosis resistance have been observed in colon cancer cell line HCT116, lung cancer cell line A549 and melanoma cell line A375, indicating that the ferroptosis regulation of CDK12 is dependent on its kinase activity." (PMID 38736108, 2024). "CDK12 is an exploitable vulnerability in multiple types of cancer, including melanoma, making it an attractive therapeutic target." (PMID 38104154, 2023). "To characterize the mechanism of action of SR-4835, a recently described CDK12 inhibitor, we performed a genome-wide CRISPR/Cas9 loss-of-function screen in A375 melanoma cells." (PMID 38104154, 2023). "As the RAS/MAPK pathway is highly active in a large majority of melanomas, we propose that CDK12 contributes to chemoresistance by favouring the expression of genes involved in the DNA damage response." (PMID 36309522, 2022). "Inhibition of these pathways strongly synergize with CDK12 inhibitors to suppress melanoma growth, suggesting promising drug combinations for more effective melanoma treatment." (PMID 36309522, 2022).